PPARG (peroxisome proliferator activated receptor gamma)
Diseases named in the same sentence as PPARG in open-access papers (continued):
Sharing a sentence is not in itself a finding about the gene and the disease.
Insulin resistance (continued). "For example, prolonged use of PPARγ agonists can lead to receptor downregulation, resulting in secondary insulin resistance." (PMID 40926269, 2025). "Previous studies have reported similar observations, where Lut stimulates PPARγ activity and ameliorates vascular dysfunction and insulin resistance in high-fructose-fed rats." (PMID 41305657, 2025). "Forskolin predominantly upregulated PPARγ and C/EBPβ expression, while ferulic acid improved inflammation and insulin resistance via the NFκB/MAPK signaling pathways in adipocytes." (PMID 40005965, 2025). "Collectively, these data demonstrate that, during feeding, c‐Fos is a key regulator of hepatic PPARγ in the liver and that c‐Fos promotes insulin resistance in chow diet‐fed mice." (PMID 41024433, 2025). "The coordinated upregulation of the antagonistic regulators GATA3 and PPARγ in thigh fat during insulin resistance points to a complex, adaptive response aimed at maintaining adipocyte function and systemic lipid homeostasis." (PMID 41573201, 2025). "While PPARγ activation can improve insulin resistance, it also promotes the differentiation of mesenchymal stem cells into adipocytes rather than osteoblasts." (PMID 40074983, 2025). "By exploring gene-tissue interactions and signaling pathways like Wnt/β-catenin and PPARγ, the study addresses gaps in understanding the mechanisms linking diet to beta cell failure and systemic insulin resistance." (PMID 41614817, 2025). "Variants in genes related to insulin signaling, such as IRS-1 and PPARG (peroxisome proliferator-activated receptor gamma), have been shown to influence insulin resistance and BMI." (PMID 39940355, 2025). "These cytokines impair insulin signaling and destabilize C/EBPα and PPARγ, thereby further driving the proliferation of adipocytes and the development of insulin resistance." (PMID 40002389, 2025). "Several proposed mechanisms by which Se ameliorates insulin resistance include the activation of kinases involved in the insulin signaling cascade and the enhancement of peroxisome proliferator-activated receptor gamma (PPAR-γ) mRNA expression." (PMID 40564877, 2025). "EV cargo also includes miRNAs (e.g., miR-27a,miR-130b) that induce insulin resistance and alter lipid metabolism byinhibiting PPARγ and PGC1α." (PMID 39916853, 2025). "Activating peroxisome proliferator-activated receptors-γ (PPARγ) improves fat deposition in the liver, relieves insulin resistance, and reduces de novo lipogenesis in the liver." (PMID 41235615, 2025). "The dysregulation of PPARγ by CDK5 is also implicated in adipose tissue insulin resistance, with CDK5-mediated phosphorylation of PPARγ, a master regulator of adipogenesis, suppressing ADIPOQ expression as observed in our data." (PMID 40975767, 2025). "It has been shown that the 3HB ameliorates insulin resistance by inhibiting PPARγ Ser273 phosphorylation in T2D mice." (PMID 40649995, 2025). "During fat metabolism, activation of PPARG enhances FA oxidation, promotes mitochondrial β-oxidation, decreases plasma free FA levels, and reduces both fat accumulation and insulin resistance." (PMID 40670965, 2025). "Understanding the binding interfaces between SIRT1 and PPARγ is critical to developing new strategies to combat insulin resistance." (PMID 40673659, 2025). "The nuclear receptor PPARγ is a primary therapeutic target for insulin resistance and type 2 diabetes (T2D); however, its thiazolidinedione (TZD) class of PPARγ agonists have substantial safety concerns in clinical utilization." (PMID 41473291, 2025). "Many of these genes, including APOB, INSR, and PPARG, have multiple sources of supporting evidence and are implicated in known MASLD mechanisms like lipid metabolism, insulin resistance, and adiposity." (PMID 40065360, 2025). "hsa-miR-34a-5p regulates lipogenesis and adipocyte differentiation through SIRT1 (sirtuin 1) and PPARG suppression, linking it to visceral fat accumulation and insulin resistance." (PMID 40699679, 2025).
Insulin resistance (continued). "PPARγ inhibitor and PPARγ knockdown abolished the improvement of insulin resistance by Metrnl, suggesting that the increase in insulin sensitivity by Metrnl is mediated by PPARγ signaling." (PMID 40956671, 2025). "In contrast, PPARγ ameliorates insulin resistance primarily through the regulation of adipokine secretion." (PMID 40243942, 2025). "In skeletal muscle cells, miR-27a-enriched EVs induce insulin resistance by targeting the peroxisome proliferator-activated receptor gamma gene." (PMID 40001534, 2025). "The activation of PPARγ has been reported to reduce inflammation, hyperglycemia, and insulin resistance and significantly improve glucose metabolism disorders in the body." (PMID 38254542, 2024). "It was emphasized that PPARα activation can effectively alleviate dyslipidemia and that PPARγ agonists reduce insulin resistance." (PMID 39062500, 2024). "Conversely, another study showed that mice overexpressing human ApoD developed hepatic steatosis and insulin resistance over time, with the accumulation of arachidonic acid and overactivation of PPARγ believed to contribute to the pathogenesis." (PMID 38375199, 2024). "It has been reported to aggravate insulin resistance in adipocytes by targeting peroxisome proliferator-activated receptor gamma (PPARγ)." (PMID 38745315, 2024). "While agonists of this receptor, improve systemic insulin sensitivity, chronic PPARγ activation in hepatocytes can paradoxically promote insulin resistance." (PMID 39598636, 2024). "The over-SUMOylation of PPARg also initiates an endogenous SUMOylation cascade to further worsen the endothelial insulin resistance." (PMID 38540730, 2024). "It has been shown that PPARG is among the first genes divergently modified in newly onset insulin resistance." (PMID 39595621, 2024). "miR-155 is one of the miRNAs that is overexpressed in obese adipose tissue macrophages and can induce insulin resistance in adipose tissues, skeletal muscle, and liver by downregulation of PPARγ expression." (PMID 39872218, 2024). "Prolonged exposure to iAs results in glucose intolerance, insulin resistance and lower PPARγ expression in mice." (PMID 38474793, 2024). "Prevention of PPARγ Ser-273 phosphorylation in adipose tissues and skeletal muscle protects mice from insulin resistance." (PMID 38735390, 2024). "By suppressing the expression of its target gene, PPARg, miR-155 can increase glucose intolerance, systemic insulin resistance, and cellular insulin resistance." (PMID 39126035, 2024). "Research has shown that the activation of PPARγ can reduce the transfer of fatty acids to the liver, decrease insulin resistance, and inhibit the expression of IL-6 and TNF-α." (PMID 39064674, 2024). "SHBG expression has been linked to PI3K/AKT pathway function in a human cellular model of insulin resistance and to inhibition of hepatic lipogenesis in mouse models by reducing PPARγ activation." (PMID 39409124, 2024). "Angiotensin II impairs adipogenesis in VAT via PPARγ inhibition and promotes insulin resistance through activation of ERK1/2, which inhibits insulin phosphorylation of Akt." (PMID 39063184, 2024). "TGF-β/Smad3 signaling is also involved in systemic insulin resistance by regulating the expression of peroxisome proliferator-activated receptor gamma (PPAR-γ) and PPAR-γ coactivator 1 alpha (PGC-1α)." (PMID 38235326, 2024). "Adipocyte-derived exosomal miR-27a has been reported to inhibit PPARγ expression in skeletal muscle, leading to insulin resistance." (PMID 39063184, 2024). "Under pathological conditions like obesity, insulin resistance, and metabolic syndrome, PPARγ expression is significantly upregulated in hepatocytes." (PMID 39598636, 2024). "Variant pathogenic variants in the human PPARγ DBD domain can inhibit its transcriptional roles and lead to severe insulin resistance and increased diabetes risk." (PMID 38951919, 2024).
Insulin resistance (continued). "We showed the hypermethylation of the PPARG promoter, which correlated with the downregulation of PPARG expression in adipocytes with artificially induced insulin resistance." (PMID 39595621, 2024). "PPARγ is one of the three isoforms of PPARs, and is activated by thiazolidinediones such as pioglitazone and is applied for insulin resistance treatment." (PMID 38822367, 2024). "With interactions such as direct protein-protein agonism increasingly seen as targets for therapeutic intervention, identification of new cofactors, such as ZFP407, in the PPARγ pathway can reveal new drug targets for insulin resistance and T2D." (PMID 38781157, 2024). "Conversely, Metrnl overexpression yields contrary effects, curtailing lipogenesis and suppressing PPARγ expression in human adipocytes, potentially leading to hyperinsulinemia and insulin resistance." (PMID 38275393, 2024). "We additionally found that ML supplementation significantly increased the serum levels of adiponectin and leptin, two cytokines secreted during adipocyte differentiation, while promoting the expression of PPARγ and inhibiting insulin resistance." (PMID 38672381, 2024). "Cornelian cherry has been shown to enhance the expression of insulin signalling genes in adipocytes, while increasing the expression of PPARγ, therefore alleviating insulin resistance and exerting a beneficial effect on cellular metabolism." (PMID 38999920, 2024). "PPAR-γ (peroxisome proliferator-activated receptor gamma) agonists, such as pioglitazone, were initially introduced to treat insulin resistance in type II diabetes mellitus, showing the ability to reduce albuminuria." (PMID 37493956, 2024). "TNFα induces phosphorylation of PPARγ at Ser-273 in murine adipocytes subsequently promoting insulin resistance." (PMID 38735390, 2024). "Alike PPARγ, low SHBG levels have been correlated with insulin resistance and associated endocrine abnormalities." (PMID 38874666, 2024). "It has been demonstrated that excessive SUMOylation of PPARg, a mimic of a high-fat diet, leads to endothelial insulin resistance and dysfunction through the downregulation of the endothelial nitric oxide synthase–nitric oxide (eNOS-NO) pathway." (PMID 38540730, 2024). "For example, PPARα agonists treat hyperlipidemia or modulation of inflammatory response, while PPARγ agonists have potent hypoglycemic potential in patients with insulin resistance and cancer." (PMID 39062500, 2024). "PPARG is the first gene abnormally expressed due to induced insulin resistance, playing a crucial role in insulin signaling regulation and insulin sensitivity." (PMID 37475719, 2023). "Phenotypes in HGFAC-KO mice were consistent with liver-specific deletion of PPARγ, which results in reduced hepatic steatosis and impaired hepatic glucose homeostasis eventually leading to the development of peripheral insulin resistance." (PMID 36413406, 2023). "Based on present in vitro results, we propose for the first time that 3HB regulates ERK1/2 activity via HCAR2/Ca2+/cAMP/PKA/Raf1, optimizing PPARγ function from the aspect of post-translational modification to reduce insulin resistance." (PMID 37230992, 2023). "Collectively, 3HB ameliorates insulin resistance in type 2 diabetic mice through a pathway of HCAR2/Ca2+/cAMP/PKA/Raf1/ERK1/2/PPARγ." (PMID 37230992, 2023). "The antidiabetic drug pioglitazone ameliorates insulin resistance by activating the transcription factor PPARγ." (PMID 37923895, 2023). "Increased expression of p-IRS(Ser 307) (P < 0.01) a hall mark of insulin resistance and PPARγ (P < 0.05) – an indicative of PCOS was also reduced remarkably because of the treatment with these bioactive compounds in PCOS-IR cells." (PMID 36932437, 2023). "Elevated Menin was found to suppress PPARγ activity, improving insulin resistance and attenuating the development of diet-induced NAFLD." (PMID 37740216, 2023).
Insulin resistance (continued). "Pomegranate has the ability to reduce insulin resistance via the peroxisome proliferator-activated receptor gamma (PPARγ) and therefore regulates abnormal oxidative stress in macrophages and inhibits pathological cardiac changes." (PMID 36644578, 2023). "PPARγ increases glucose uptake, lipid uptake, and glucose oxidation, as well as decreases insulin resistance and free fatty acid concentration." (PMID 37765290, 2023). "Troglitazone was a peroxisome proliferator‐activated receptor γ (PPARγ) agonist and insulin sensitizer, mainly used in the treatment of type 2 diabetes mellitus and insulin resistance." (PMID 38156385, 2023). "The relation between PPARγ and insulin resistance has been extensively studied, particularly since the discovery of its S273 phosphorylation." (PMID 37189379, 2023). "It has been shown that abscisic acid is a novel PPARγ agonist that improves insulin resistance and suppresses systemic inflammation in obese mice." (PMID 36904078, 2023). "Examples are GCK-related hyperglycemia, HNF1Adiabetes, INSR-severe insulin resistance, PPARG-lipodystrophy, mt.3243 A > G syndrome." (PMID 37794142, 2023). "Phosphorylation of PPARγ at S273 induces insulin resistance by upregulating Gdf3 expression and inhibiting BMP signaling pathway." (PMID 37143582, 2023). "This study delved into a comprehensive analysis of how PPARγ signaling affects the exercise-induced improvement of insulin resistance (IR) and non-alcoholic fatty liver disease (NAFLD), along with its underlying mechanism." (PMID 37907845, 2023). "Phosphorylation of Ser273 in PPARγ by CDK5 (cyclin-dependent kinase 5) is associated with obesity and insulin resistance and this finding spurred research toward developing small molecules to inhibit this modification." (PMID 37893070, 2023). "Specifically, PPAR-gamma activation, a result of PPARG gene expression, enhances glucose tolerance and insulin sensitivity in both diabetes mellitus patients and animal models of insulin resistance." (PMID 38201926, 2023). "In mice, muscle-specific deletion of PPARγ resulted in severe insulin resistance with milder defects in adipose tissue and liver, altered adipokine expression, increased adiposity, hyperinsulinemia, glucose intolerance, and hypertriglyceridemia." (PMID 37334286, 2023). "Adipose tissue macrophage (ATM)-EVs are shown to be over-expressed with miR-155 under obese conditions, which targets PPARγ in adipocytes, myocytes, and primary hepatocytes, leading to glucose intolerance and insulin resistance." (PMID 37566042, 2023). "CO fruit can significantly increase PPARG expression in cells, reversing insulin resistance, enhancing glucose uptake after insulin stimulation." (PMID 37475719, 2023). "Studies have shown that RBP4 can lead to insulin resistance and affect protein anabolism in skeletal muscle indirectly, particularly under the stimulation of peroxisome proliferator-activated receptor-gamma (PPARγ) agonists." (PMID 37525169, 2023). "The interaction between PPARγ and NF-κB is a signaling pathway that connects insulin resistance, metabolic syndrome, and inflammation." (PMID 37324274, 2023). "Thiazolidinediones (TZDs), well-known PPARγ agonists, are drugs that improve insulin resistance in type 2 diabetes." (PMID 36339572, 2022). "Deficiency of adipose tissue Metrnl exacerbated high fat diet induced hypertriglyceridemia, whereas adipose tissue-specific overexpression of Metrnl attenuated hypertriglyceridemia and insulin resistance in mice through PPARγ signaling." (PMID 36133314, 2022). "PPARα mainly influences fatty acid metabolism, and its activation lowers lipid levels, while PPARγ is mostly involved in the regulation of adipogenesis, the energy balance, and lipid biosynthesis, and its activation affects insulin resistance." (PMID 36501129, 2022).
Insulin resistance (continued). "Recently in vivo and in vitro studies have shown methylation of DNA and histone modifications both connect changes in insulin signaling genes and PPARγ itself to insulin resistance." (PMID 34863942, 2022). "Numerous studies confirm the reduction of PPARG expression in insulin resistance both in studies on cell lines and in human studies." (PMID 35684107, 2022). "Activation of PPARγ by thiazolidinediones can reduce insulin resistance and hyperglycemia in type 2 diabetes, but these drugs can also cause weight gain." (PMID 36501129, 2022). "Thiazolidinediones (TZDs), developed using scanning rodent models of insulin resistance, are diabetes treatment drugs that target PPARγ." (PMID 35957821, 2022). "Top loci in this cluster included several well-known associations with WHRadjBMI and insulin resistance including COBLL1, RSPO3, PPARG, and DNAH1012,47,54,55." (PMID 35773277, 2022). "Thiazolidinedione (TZD) activates the peroxisome proliferator-activator receptor gamma (PPARγ) and improves insulin resistance and has been used for lowering blood glucose in patients with type 2 diabetes mellitus." (PMID 36558989, 2022). "Accordingly, further understanding of how TZDs trigger robust PPARγ activation, as well as alternative approaches for regulating PPARγ signaling, will potentially provide improved therapies for insulin resistance." (PMID 35473936, 2022). "The mechanism of reversing insulin resistance in the investigated cells likely results from the stimulation of PPARG expression after the addition of CM fruits." (PMID 35684107, 2022). "PPARγ is a member of the peroxisome proliferator-activated receptors, and its famous function is to regulate fat cell differentiation, body immunity, and insulin resistance." (PMID 35690612, 2022). "Thiazolidinedione (TZD) compounds are a class of PPARγ ligands that improve insulin resistance by promoting adipocyte differentiation via PPARγ activation in adipocytes with a high capability to utilize glucose." (PMID 36144514, 2022). "In diabetic patients and in animals with insulin resistance, PPARγ improves both glucose tolerance and cellular insulin sensitivity." (PMID 36233271, 2022). "Mechanistically, downstream of RhoA/ROCK-mediated F-actin assembly, nuclear translocation of MRTF-A suppresses the expression of IRS1 and PPARγ in hypertrophic adipocytes, contributing to adipocyte dysfunction and insulin resistance." (PMID 35769086, 2022). "PPARG has the potential to improve insulin resistance since its activation increases peripheral tissue sensitivity to insulin." (PMID 36289871, 2022). "Adipocyte-specific knock-down of CUL4B-RING E3 ligase (CRL4B), which promotes polyubiquitination and proteasomal degradation of PPARγ, can ameliorate high fat-induced glucose intolerance and insulin resistance, as well as enhance adipocyte insulin sensitivity." (PMID 36551260, 2022). "They ameliorate insulin resistance by activating peroxisome proliferator-activated receptor-gamma (PPAR-γ)." (PMID 35028008, 2022). "Many studies have confirmed that PPARG expression is reduced in insulin resistance, in both cell and human studies." (PMID 36235858, 2022). "The expression of adiponectin in adipose tissue can also be induced by thiazolidinediones, a family of molecules used in treatments against insulin resistance and type II diabetes such as rosiglitazone, a PPARγ agonist known for its insulin-sensitizing role." (PMID 36078135, 2022). "SIRT1 deacetylates lysine residues of PGC-1α and PPARγ, promotes WACs browning, and improves insulin resistance." (PMID 35416120, 2022). "In perfect agreement with our model’s predictions, a mechanistic study showed that chamomile ameliorates insulin resistance through transcriptional stimulation of PPARG and PPARA in the adipose tissue and liver, respectively." (PMID 36160451, 2022).